ACTB (actin beta)
Diseases named in the same sentence as ACTB in open-access papers (continued):
Sharing a sentence is not in itself a finding about the gene and the disease.
lymphoma (10 papers, 2016 to 2024). A malignant (clonal) proliferation of B- lymphocytes or T- lymphocytes which involves the lymph nodes, bone marrow and/or extranodal sites. "Within the different types of lymphoid cancers ACTB mutations are most frequent in diffuse large B-cell lymphoma (DLBCL) and ACTG1 mutations in multiple myeloma." (PMID 32349449, 2020). "cBioPortal data indeed indicate a single mutation in B-ALL, however, we show that the ACTB mutations found in lymphoid cancers almost exclusively occur in mature B-cell neoplasms." (PMID 32349449, 2020). "Compared to other lymphoid cancer types, mutations in ACTB and ACTG1 are most frequent in DLBCL and multiple myeloma, respectively." (PMID 32349449, 2020). "Within the different types of lymphoid cancers ACTB mutations are for the most part associated with DLBCL." (PMID 32349449, 2020). "In the realm of hematological malignancies, mutations in actin genes ACTB and ACTG1 are predominantly linked to lymphoid cancers." (PMID 38240686, 2024). "Potential novel candidate biomarkers in canine lymphoma were ACTB, β2M, TIMP-1, CD44 antigen, Ig heavy chain V region GOM, APOC1, and APOH." (PMID 35765478, 2022). "The first reported serum proteins in canine lymphoma were ACTB, Ig heavy chain V region GOM, TIMP-1, APOH, CD44, APOC1, and β2M." (PMID 35765478, 2022). "Using patient data available at cBioPortal we show that mutations in ACTB and ACTG1 in hematological cancers all occur in lymphoid cancers." (PMID 32349449, 2020). "To identify subtypes of lymphoid cancers potentially enriched in somatic mutations in ACTB and/or ACTG1 we selected ‘cancer type detailed’ in the ‘cancer types summary’ tab after querying the lymphoid cancers in cBioPortal." (PMID 32349449, 2020). "Differently higher serum proteins in canine lymphoma were observed in beta-actin cytoplasmic 1 (ACTB, p=0.04), Hp (p=0.002), beta-2 microglobulin (β2M, p=0.007), beta-2 glycoprotein 1 (APOH, p=0.03), metalloproteinase inhibitor 1 (TIMP-1, p=0.03), and CD44 antigen (p=0.02)." (PMID 35765478, 2022). "Six candidate increased proteins in canine lymphomas were beta-actin cytoplasmic 1 (ACTB, p=0.04), haptoglobin (p=0.002), beta-2 microglobulin (aaaaaaaa2M, p=0.007), beta-2 glycoprotein 1 (APOH, p=0.03), metalloproteinase inhibitor 1 (TIMP-1, p=0.03), and CD44 antigen (p=0.02)." (PMID 35765478, 2022). "In malignant lymphomas, mutations can influence the correct assembly of the cytoskeleton and thus the ability to migrate (e.g., ROCK1 mutation in Hodgkin lymphoma, RHOA mutations in AITL and DLBCL, and ACTB mutations in DLBCL)." (PMID 34680356, 2021). "Indeed, focusing on the absolute counts instead of the frequencies reveals that all 58 patients with mutations in ACTB and/or ACTG1 suffer from a type of lymphoid cancer." (PMID 32349449, 2020). "We focused on ACTB and ACTG1 in blood cancers by selecting studies on lymphoid cancers and myeloid cancers in cBioPortal." (PMID 32349449, 2020). "ACTB, aaaaaaaa2M, APOH, TIMP-1, CD44 antigen, Ig heavy chain V region GOM, and APOC1 are novel candidate proteins and might serve as a lymphoma biomarker in dogs." (PMID 35765478, 2022). "Within studies on hematological cancers, mutations in ACTB and ACTG1 are associated with lymphoid cancers since none have currently been reported in myeloid cancers." (PMID 32349449, 2020). "Within hematological cancers, mutations in ACTB and ACTG1 are exclusively associated with lymphoid cancers and not with myeloid cancers." (PMID 32349449, 2020).
developmental delay (9 papers, 2017 to 2025). "Pathogenic variants of ACTB are commonly associated with Baraitser-Winter prefrontal brain syndrome, resulting in severe, persistent dystonia, developmental delays and sensorineural hearing loss." (PMID 33795012, 2021). "We report on a patient that harbors an already published de novo variant in ACTB with severe, intractable dystonia, developmental delay, sensorineural hearing loss, and brain changes on MRI significant for hyperintensities in the caudate nuclei and putamen." (PMID 28487785, 2017). "Pathogenic variants in ACTB are most frequently associated with Baraitser-Winter cerebrofrontofacial syndrome (BWCFFS), which is characterized by developmental delay, craniofacial dysmorphism, and central nervous system abnormalities." (PMID 41141068, 2025). "From the analysis of the ACTB identified, the review showed some common clinical characteristics, such as facial dysmorphisms, motor and developmental delay, dystonia, cleft lip and palate, ocular, cardiac, gastrointestinal and renal abnormalities." (PMID 38592426, 2024). "By contrast, 7p21.1 microdeletion encompassing ACTB often presents with milder and less specific dysmorphic features, variable developmental delay, and white matter abnormalities without severe cortical malformations." (PMID 41141068, 2025). "Variants of ACTB have been associated with three neurological disorders, including Baraitser–Winter syndrome 1 (BRWS1 (MIM: 243310)), dystonia-deafness syndrome 1 (DDS1 (MIM: 607371)), and thrombocytopenia 8 (THC8), with dysmorphic features and developmental delay (MIM: 620475)." (PMID 40677923, 2025).
ovarian carcinoma (9 papers, 2014 to 2025). A malignant neoplasm originating from the surface ovarian epithelium. "The relationship between the ratio of TNFRSF14/ACTB mRNA expression and clinicopathological parameters in ovarian cancer tissues." (PMID 40105652, 2025). "The relationship between the ratio of XBP1/ACTB mRNA expression and clinicopathological parameters in ovarian cancer tissues." (PMID 40105652, 2025). "Except for ACTB in Thymoma and Ovarian Cancer, the methylation levels of DRGs in pan-cancer had different degrees of negative correlation with mRNA expression." (PMID 38235128, 2023). "Although trends indicate an increase in ACTB and THBS1 expression in ovarian cancer patients compared to healthy control subjects, differences in ΔCq values were not significantly different due to low sample numbers." (PMID 34868914, 2021). "The highest increases of PARP1/ACTB mRNA ratios were induced by the most potent PARP inhibitor, the bilactamic steroid alkylator ASA-B, reaching at 120-fold increase in SKOV-3 and a 42–50-fold increase in UWB1.289, UWB1.289 + BRCA1 and OVCAR-3 human ovarian cancer cells." (PMID 34440232, 2021). "From the 12 candidate reference genes we studied, the combination use of ACTB, PPIA, RPLP0, and TBP was identified as a relatively superior normalization strategy, while GAPDH was insufficient for accurate normalization when considering its overexpression in ovarian cancer." (PMID 24776823, 2014). "Given that HRPT1 and B2M were expressed differently in the 50 specimens, which suggested that these two genes were not eligible reference genes, the combination of ACTB, RPLP0, PPIA, and TBP was recommended for use in epithelial ovarian cancer studies." (PMID 24776823, 2014).
Stroke (9 papers, 2021 to 2025). Sudden impairment of blood flow to a part of the brain due to occlusion or rupture of an artery to the brain. "In the future, the association between ACTB methylation and risk of stroke, as well as its correlation with expression, will be further investigated in our new prospective cohort study." (PMID 34054407, 2021). "In this study, we evaluated the association between ACTB methylation and the risk of stroke in a nested case-control study." (PMID 34054407, 2021). "We firstly reported the blood-based ACTB methylation as a marker for the risk evaluation and preclinical detection of stroke, which can be further modified by age and drinking." (PMID 34054407, 2021). "So far, no data are available about the association between blood-based ACTB methylation and stroke, especially in prospective studies." (PMID 34054407, 2021). "This study aimed to explore the relationship between DNA methylation of the ACTB gene in peripheral blood and stroke risk in a nested case-control study from a prospective cohort with a total of 11,151 subjects." (PMID 34054407, 2021). "The increase in ACTB levels in EV from stroke patients may be linked to cytoskeletal remodeling, inflammatory responses, or stress conditions." (PMID 40672462, 2025). "Thus, we further examined the association between ACTB methylation and stroke stratified by 65 years, the age which is widely used for stroke risk stratification and stroke prevention in most guidelines." (PMID 34054407, 2021). "Additionally, our previous studies have shown that ACTB variants may confer genetic susceptibility to stroke and diabetic kidney disease (DKD) in a Chinese Han population." (PMID 34054407, 2021). "The methylation level of ACTB_CpG_4.5 was inversely correlated with age in controls (Spearman rho = -0.193, P = 0.020), but not with age in stroke cases, which indicated that ACTB_CpG_4.5 methylation might be an age-dependent factor for the risk of stroke." (PMID 34054407, 2021). "However, we have to admit that our results on ACTB hypomethylation-related risk of stroke were based on a relatively small sample size, which power although could be compensated by the randomly selected samples from the whole prospective cohort." (PMID 34054407, 2021). "ACTB, a key cytoskeletal component, is crucial in stroke pathology as its disruption impairs neuronal structure and function, affecting stroke outcomes and recovery." (PMID 39595569, 2024). "Our previous study has identified blood-based ACTB hypomethylation as early as 2 years before the clinical status of stroke in a prospective cohort study." (PMID 36061541, 2022). "Further prospective studies with larger sample sizes and different stroke subtypes are needed to evaluate the potential value of ACTB methylation as a biomarker for stroke." (PMID 34054407, 2021). "In summary, this study disclosed a significant correlation between preclinical altered ACTB methylation in blood and stroke, and thus suggested the potential of blood-based ACTB methylation for the early detection and even prevention of stroke." (PMID 34054407, 2021). "This hypomethylation of ACTB in blood became significant 1.5 years before the clinical indication of stroke, and was even more pronounced 1.32 years and 1 year preclinically." (PMID 34054407, 2021). "The mean of the relative expression levels of ACTB in the leukocytes of stroke cases was 1.10-fold higher than in the controls (ACTB relative expression, mean ± SD of cases: 1.15 ± 0.36, mean ± SD of controls: 1.05 ± 0.38)." (PMID 34054407, 2021). "Nevertheless, only CpG_14 located in the fourth exon of the ACTB gene showed a significant correlation with stroke." (PMID 34054407, 2021). "The methylation level of ACTB was quantitatively determined by mass spectrometry in 139 stroke cases who developed stroke within 2 years after recruitment and 147 age- and sex-matched controls who remained stroke-free in a median follow-up of 2.71 years." (PMID 34054407, 2021).
Stroke (continued). "We thus analyzed the ACTB expression from the 46 stroke cases and another 48 age- and sex- matched healthy controls from the same prospective cohort study." (PMID 34054407, 2021). "Lower methylation level of the ACTB is found in stroke patients." (PMID 37699956, 2023). "Previous study has revealed that blood-based hypomethylation of β-actin (ACTB) was associated with increased risk of stroke, but not reported in CHD yet." (PMID 36061541, 2022). "Recent study showed that preclinical altered blood-based ACTB methylation had a significant correlation with stroke, which suggested that it might be a potential regulatory indicator for early detection and even prevention of stroke." (PMID 36340795, 2022). "Since the onset time of stroke may influence the methylation levels of ACTB, we performed additional analyses comparing controls and stratified stroke cases by time of onset." (PMID 34054407, 2021). "However, little is yet known about the epigenetic impact of ACTB on the initiation and progress of stroke." (PMID 34054407, 2021). "None of the other 10 CpG sites in the ACTB amplicon showed an association with stroke at any time of onset." (PMID 34054407, 2021). "Based on these findings, we suggest that the methylation level of ACTB in blood DNA might be a preclinical marker in stroke and reflect a response to stroke in the years preceding clinical diagnosis, which is also supported by previous studies using pre-diagnostic blood samples." (PMID 34054407, 2021). "Although we have observed a slightly increased expression of ACTB in the preclinical stroke cases, it was not significant due to the limited sample size." (PMID 34054407, 2021). "To date, no studies have directly analyzed ACTB levels in stroke patients." (PMID 40672462, 2025). "So far, no public DNA methylation database has ever reported the ACTB methylation in stroke." (PMID 34054407, 2021). "In addition, the methylation levels of ACTB_CpG_2.3 and ACTB_CpG_7.8 showed inverse correlation with current drinking status in controls (Spearman rho = -0.191 and -0.242, respectively, P < 0.020 for both), but not with drinking status in stroke cases." (PMID 34054407, 2021). "However, some studies showed that ACTB might not be an optimal reference gene for the normalization of gene expression in whole blood under the pressure of certain diseases such as stroke, which induces alterations in the cellular composition of the peripheral immune system." (PMID 34054407, 2021).
Thrombocytopenia (9 papers, 2018 to 2025). A reduction in the number of circulating thrombocytes. "ACTB-associated pleiotropic malformation syndrome and ACTB-associated syndromic thrombocytopenia can be caused by single-point missense mutations, truncating mutations, frameshift mutations, or deletion." (PMID 38446501, 2024). "Here, the authors report of a syndromic thrombocytopenia caused by variants in ACTB exons 5 or 6 that compromise the organization and coupling of the cytoskeleton, leading to impaired platelet maturation." (PMID 30315159, 2018). "In this instance, a patient with a de novo missense mutation in exon 6 of ACTB presented with moderate intellectual disability, abnormal white blood cell counts with recurrent infections, and thrombocytopenia." (PMID 30315159, 2018). "Our results define an ACTB-associated clinical syndrome with a distinct genotype-phenotype correlation and delineate molecular mechanisms underlying thrombocytopenia in this patient cohort." (PMID 30315159, 2018). "Thrombocytopenia was tested in P3 after identification of the ACTB mutation." (PMID 30315159, 2018). "The macro-thrombocytopenia observed in our patient aligns with findings from a previous study, which identified impaired platelet development and maturation in six patients with various variants in exons 5 and 6 of ACTB, all presenting with syndromic thrombocytopenia." (PMID 40748410, 2025). "This method allowed us to identify a cytoskeletal phenotype unique to ACTB-AST, whereby a specific subset of thrombocytopenia-associated ABPs is recruited to mutant β-CYA bundles." (PMID 30315159, 2018). "Overall, our fibroblast experiments uncovered a membrane-associated cytoskeletal filament population uniquely affected in ACTB-AST cells, comprising β-CYA and thrombocytopenia-associated ABPs, such as α-actinin 1, NM-2A and filamin A." (PMID 30315159, 2018). "As such, we sought to define a shortlist of ABPs affected by variant β-CYA in P4 and P5 fibroblasts that contribute to the thrombocytopenia phenotype observed in ACTB-AST patients." (PMID 30315159, 2018). "The mutations do not affect protein stability and abundance, unlike mutations associated with ACTB‐associated thrombocytopenia, which is a different syndrome from BWCFF." (PMID 39930656, 2025). "Recently, pathogenic variants in exons 5 and 6 of ACTB have been reported in six patients presenting with clinical symptoms different from BWCFF, particularly thrombocytopenia which is caused by inhibited platelet maturation as a result of a compromised microtubule organization." (PMID 35572556, 2022). "Further, we could not link thrombocytopenia in ACTB-AST patient cells to differentiation or podosome defects." (PMID 30315159, 2018).
Dystonia (8 papers, 2017 to 2025). An abnormally increased muscular tone that causes fixed abnormal postures. "GPi-DBS was also demonstrated to have beneficial effect in ACTB-associated dystonia-deafness syndrome." (PMID 33446253, 2021). "ACTB p.Arg183Trp heterozygosity has been reported in six patients to cause combined infant-onset deafness and dystonia manifesting in adolescence or young adulthood." (PMID 29788902, 2018). "In this patient with dystonia-deafness syndrome caused by ACTB p.Arg183Trp heterozygosity, unprecedented brain imaging findings strongly indicate striatal neuronal/dopaminergic dysfunction as the underlying cause of the dystonia." (PMID 29788902, 2018). "We hypothesize that this particular ACTB gain-of-function variant renders striatal neurons vulnerable to cell death as a consequence of changing demands on striatal neurons and connections occurring during adolescence and thereby causes dystonia." (PMID 29788902, 2018). "We have presented a now 23-year-old woman with dystonia-deafness syndrome and mild developmental defects compatible with a BWCFF syndrome, caused by the ACTB p.Arg183Trp variant." (PMID 29788902, 2018). "Three out of 10 patients (with GNAO1, ACTB and KMT2B variants) could be considered for surgical interventions when medical therapies for dystonia fail." (PMID 33446253, 2021). "ACTB sequencing should be included in the work-up of dystonia-deafness syndrome." (PMID 29788902, 2018). "Additionally, likely pathogenic or pathogenic variants were found in ATP1A3 (n = 5) and GNAO1 (n = 1) for genes causing combined dystonia, as well as ACTB (n = 1), IRF2BPL (n = 1), SPR (n = 1), and TUBB4A (n = 3) for genes linked to dystonia with other neurological or systemic features." (PMID 40533913, 2025). "Therefore, patient 31 with ACTB mutation will be planned for GPi-DBS as the dystonia fails to improve on 5 medications (baclofen, trihexyphenidyl, L-dopa, clonazepam, gabapentin)." (PMID 33446253, 2021).